IFNG (interferon gamma)
Diseases named in the same sentence as IFNG in open-access papers (continued):
Sharing a sentence is not in itself a finding about the gene and the disease.
infection (continued). "In the none-infection group of infants and children, the CD4+IFNγ+TNFα+ double producers were identified to be similar across different ages (left)." (PMID 32849561, 2020). "Yet, other reports showed therapeutic effects of administering recombinant IFNγ early during IAV infection and demonstrated important protective roles for endogenous IFNγ against IAV during a recall infection or in mice lacking Nos2 expression." (PMID 32117259, 2020). "Ex vivo, BAL CD2+ γδ T cells, without H1N1pdm09 stimulation, secreted IFNγ and TNF early post infection with the highest frequency of 0.6% IFNγ and 1.6% TNF at 3 DPI." (PMID 33603740, 2020). "After 48 h in culture without infection, hiPSC-derived trophoblasts from both CZS-affected and non-affected twins were able to secrete IFNA2 and IFNG, whereas IFNL1 was not detectable." (PMID 32745093, 2020). "Although DC-derived IL12 is important for secretion of IFNγ in vivo, it alone is not sufficient to protect the host, as Myd88−/− mice that were administered recombinant IL12 post-infection did not survive infection." (PMID 33178630, 2020). "On day 7 post infection with 100 cfu LVS, we detected 5–10 IFNγ-producing cells per 106 cells upon antigen stimulation, while no IFNγ-producing cells were observed in the non-stimulated cells." (PMID 31443439, 2019). "On average 2.1 and 3.2 times more IFNG were produced by bMDM treated with IL10 siRNA rather than NTC siRNA during AF2122/97 and G18 infection, respectively." (PMID 31527895, 2019). "We confirm increased production of Th1 cytokines IFNγ, TNF, IL-12, IL-23, and IL-1β in the proximal ileum in B6 mice upon infection, while absence of IL-33R/ST2 attenuated the Th1 cytokine response." (PMID 31057534, 2019). "Although upon infection P25 mice present a greater increase in the proportion of activated CD4+ T cells, there are no signs of in vivo higher production of IFNγ or of immunopathology in comparison to WT mice." (PMID 29499041, 2018). "This infection state is currently (and perhaps imperfectly) defined by the presence of a positive tuberculin skin test (TST) and/or interferon gamma release assay (IGRA), but no detectable clinical disease symptoms." (PMID 30319657, 2018). "This difference was associated with global CD4+ T cell preservation and greater interferon gamma (IFN-γ) mRNA expression, but not cytotoxic T lymphocyte responses in co-infected cats relative to cats with single FIV infection." (PMID 29677149, 2018). "While we did not observe significant differences in expression of IFNγ, TNF or IL-6, as compared to macrophages isolated after primary Lm-gp61 infection, heterologous challenge resulted in a significant induction in IL-12p35 expression by splenic macrophages." (PMID 29438281, 2018). "The combined action of TNFα and IFNγ 14-folded the NO2- generation in the non-infected in vitro mucosal membranes (p<0.001), and infection further increased it (p<0.001)." (PMID 30252907, 2018). "IFNγ production was significantly higher in patients with DF as opposed to DHF, especially during early infection." (PMID 30273352, 2018). "This difference was associated with global CD4+ T cell preservation, greater interferon gamma (IFN-γ) mRNA expression, and no cytotoxic T lymphocyte responses in co-infected cats relative to cats with a single FIV infection." (PMID 29677149, 2018). "After the second infection, although the DRI group had no IFNγ, all the pre- and probiotic interventions induced detectable levels, with the highest effect being in the SYN group again." (PMID 29942312, 2018). "In the context of infection, most likely, the DP3 cells in Ifnγ−/− mice mature into CD8+ SP cells while not being replenished by DP2, hence resulting in a lower DP3 pool." (PMID 28091621, 2017).
infection (continued). "Finally, those pigs euthanized after challenge with the highest levels of viremia and IL-10 (pigs A4, A5, C4 and F5, but not C5), also displayed a high increase of IFNγ in serum before death that may be interpreted as a failed last attempt of immune system for controlling last stages of infection." (PMID 27908827, 2017). "Nonetheless, the absence of IFNγ induction in IL-33 KO and the expressions of CXCL10 and CXCL11 were strongly upregulated during L2-MHV3 infection especially in IL-33 KO background at 72 h PI." (PMID 28607531, 2017). "Nonetheless, only one mouse of this group died through the infection (right), demonstrating once more that CD4+ T cells are capable of protecting against R. typhi without the capability to produce IFNγ." (PMID 28222146, 2017). "Immunization of mice with the JgD anti-HSV vaccine without infection elicited IL12p70, IL17, and IFNγ serum responses in mice." (PMID 28459074, 2017). "MV-infected CD46+/IFNγ-KO explants displayed significantly lower nestin expression compared to MV-infected CD46+ mice, which displayed no change with infection." (PMID 27178303, 2016). "An intermediate amount of infectious virus was produced throughout the course of infections with IFNγ treatment (106–107 PFU/ml) indicating the establishment of persistent, not latent, infection." (PMID 26809031, 2016). "Together, these results demonstrate that activation of STAT signaling molecules does not differ significantly early in infection (3 dpi), but that STAT1 and STAT2 phosphorylation occurs later infection in CD46+ and CD46+/IFNγ-KO explants." (PMID 27178303, 2016). "In PEC, the numbers of IFNγ+ cNK cells expressing inhibitory receptors Ly49I or CD94/NKG2A and activating receptors Ly49H, Ly49D increased significantly after cps1-1 infection and not significantly after RH and ME49 infections." (PMID 27721814, 2016). "Although, infection with multiple DENV-serotypes increased with age, DENV-NS3 specific IFNγ responses did not increase significantly with age (Spearmans r = 0.05, p = 0.42)." (PMID 25875020, 2015). "For the MP287/03 Mbv infection, comparable low levels of IL-1β were found in cell supernatants from C57BL/6 and P2X7R−/− mice, but the lack of P2X7R resulted in an increase of IFNγ and a decrease of IL-10." (PMID 24991816, 2014). "In conclusion, induction of a balanced Th1/Th17 response and production of key effector cytokines, such as IFNG, IL2, IL17, IL21, IL22 and IL23A was observed in animals that controlled infection, regardless of previous BCG-vaccination." (PMID 24505407, 2014). "The robust elevation of IFNγ levels in the serum of unprotected animals as a clear indication of immune pathology rather than immune protection, as previously shown for VARV infection of nonhuman primates." (PMID 25350003, 2014). "Analysis of CD8+ T cells showed modest increases in CD8+IFNγ+ and CD8+MIP-1β+ T cells at various time-points by subjects post initial infection, but no pattern was evident post initial infection." (PMID 25397604, 2014). "Most importantly, increased IFNγ production in absence of type I IFN responsiveness was delayed and less pronounced after i.g. compared to i.p. infection." (PMID 23840314, 2013). "The percentages of IFNγ-producing NKT cells and NK cells in EBI3−/− mice were comparable to those from wild-type mice, indicating that there is no significant role of EBI3 in the induction of IFNγ from NK and NKT cells after Lm-Ova infection." (PMID 24068935, 2013). "Accordingly, IEC isolated from IFNγ−/− neonatal mice did not significantly upregulate the expression of CXCL9 and CXCL10 during the infection whereas other chemokines such as CCL3, CCL4 and CCL5 were still upregulated." (PMID 24367259, 2013). "Expression of TNFα, IL1b, IFNγ, TGFβ and IL10 was still significantly upregulated in the infected animals compared to the non-infected 7 days after infection." (PMID 22815907, 2012).
infection (continued). "Infection with either pathogen does not affect native Stat-1 expression, however EHEC prevented Stat-1 tyrosine phosphorylation in response to IFNγ stimulation." (PMID 22253910, 2012). "Because RIG-I failed to be upregulated by S. flexneri early during infection, it is possible that greater RIG-I expression in the presence of IFNγ accounts for the ability of RIG-I to ultimately restrict S. flexneri growth." (PMID 22912573, 2012). "No decrease was observed up to 4 days after infection, either in RM-1 cells or in RM-1-PSMA clone 3 cells; these results indicate that there is no direct effect of IFNγ on cellular viability in vito." (PMID 23056548, 2012). "Most recently, it was shown that infection of cells with type II Pru or NTE parasites does not inhibit IFNγ-induced STAT1 trafficking into the nucleus." (PMID 23240025, 2012). "Further LVE studies were conducted at 6 and 12 hours post-infection to assess ‘early’ CTL recognition of endogenous Nef and Gag epitopes but no IFNγ responses were observed." (PMID 21589893, 2011). "It is worthy of note that at late hours of infection, though engaged IFNγR1 and IFNγR2 were simultaneously present in the non-raft fractions, they could not generate any productive interaction as evidenced by the complete absence of IFNγ triggered CoIP and/or phosphorylation signal." (PMID 21931549, 2011). "Our finding of capacity within the innate system for IFNγ production suggests that during acute infections with Salmonella, this capacity may suffice and priming of the acquired T cell response through prior exposure/infection or vaccination may not be essential." (PMID 21048923, 2010). "We also stimulated PBMC from HIV infected individuals with SEB to determine if CD57− memory CD4+ T cells producing IFNγ and MIP-1β had lower levels of infection than those that produced IFNγ, but no MIP-1β." (PMID 19876388, 2009). "Immune monitoring post-infection by using PBMC and in vitro stimulation with PPD or ESAT6-CFP10 fusion protein revealed reduced IFNγ release from vaccine groups as compared to non-vaccinated controls." (PMID 19367339, 2009). "Within 12 hours after infection of these naïve mice, approximately 2% of the memory SMARTA CD4+ T cells were actively producing IFNγ, but those responding cells showed no CFSE dilution." (PMID 18404208, 2008). "Perforin, but not interferon gamma, was required for clearance of MNV infection by adoptively transferred T lymphocytes from vaccinated hosts." (PMID 19079577, 2008). "The cytokine profile measured in BALF from adult and weanling mice mirrored the inflammatory profile, with adult mice showing increased levels of TNFα, IFNγ, MCP-1, IL-6 and VEGF at 7 d post infection but not at 5 d (not measured at 10 d)." (PMID 16324223, 2005). "In keeping with inflammatory cell numbers, weanling mice did not have elevated TNFα, IFNγ, MCP-1 or IL-6 in BALF at any timepoint, although VEGF was elevated at 7 d post infection." (PMID 16324223, 2005). "Regardless of the antigen tested, IFNγ release was generally low following stimulation of lung leukocytes from unvaccinated mice infected with BK80, UgCl302, or PMH1063, which has been seen previously with KN99 infection." (PMID 41440711, 2025). "However, humans lack TLR11/12 and IFNγ-inducible IRGs, and Toxoplasma ROPs that determine virulence in rodents (ROP5/ROP18) have not yet been shown to play a role in human infection." (PMID 41452934, 2025). "Specifically, following 5e4 PFU infection, PEP-null and PEP-R619W mature splenic NK cells had less CD107a, a marker of degranulation, increased perforin, and no detectable difference in IFNγ compared to PEP-WT mature splenic NK cells." (PMID 40791464, 2025). "With 1e5 PFU infection, PEP-R619W mature splenic NK cells had reduced degranulation marker CD107a, increased perforin, and an increase in frequency, but not expression, of IFNγ compared to PEP-WT and PEP-null mature splenic NK cells." (PMID 40791464, 2025).
infection (continued). "Finally, there was a group of cytokines and chemokines: TNF, IFNγ, CCL5, CXCL9, CXCL10 and CXCL13, which were early after infection elevated in the vaccinated but not detectable in the naive animals, suggesting an adaptive immune response as the trigger." (PMID 39472590, 2024). "NK cells may control infection directly by their cytolytic functions and only partially by relying on their recruitment of other immune cells through MIP-1β, but not IFNγ production." (PMID 38585993, 2024). "Together these data suggest that IFNγ and TNFα but not perforin are required for control of CCHFV during the acute disease, while TNFα and perforin may impair clearance of the infection at later timepoints." (PMID 37866114, 2023). "The results suggest that the test could be useful in resolving the infection status of IR animals, thereby removing SICCT or IFNγ negative infected animals earlier and improving the efficiency of bTB control and eradication." (PMID 36726018, 2023). "We found that after infection, cells from patients with AUD had a significant decrease in transepithelial resistance (TER) and showed enhanced secretion of several proinflammatory cytokines including TNFα, IL-1β, and IFNγ as compared with non-AUD cells." (PMID 37786945, 2023). "However, comparisons between vaccinated mice showed that H7N7 infection did not significantly increase levels of CCL2 (p = 0.94), IFNγ (p = 0.97), IL1β (p = 0.52), and IL-6 (p = 0.59) in the lungs compared to vaccinated mice receiving PBS." (PMID 37063291, 2023). "On the other hand, IFNγ that negatively correlates with the SOFA score, is known to be required during the host defense against pathogens, therefore contributing to a worse prognosis if the infection is not being controlled." (PMID 36536294, 2022). "In vaccine trials using vector viruses coding for ASFV proteins that were shown to induce T cell responses in splenocytes from recovered animals in vitro, there was no consistent correlation between the number of IFNγ-secreting cells and protection against virulent OURT88/1 challenge infection." (PMID 35215216, 2022). "In addition, no significant alteration in the levels of IFNγ, IL-1β, IL-4, IL-6, IL-8, IL-10, CXCL10, and TNFα was observed in peripheral blood after Vir-S74-T3Bo infection by comparing Att-S74-T3Bo-inoculated and naïve control animals." (PMID 36466866, 2022). "No increase of secreted IFNα or IFNγ was observed, consistent with reports on SARS-CoV-2 infection of hPSC-derived lung alveolar type II cells, which showed no significant induction of IFN genes by four days post-infection." (PMID 36128218, 2022). "The excessive uncontrolled inflammatory responses mainly led by IL-6, IFNγ, TNFα, CRP, D-dimer, VES, and the lack of vitamin D (pre-hormone D) were common clinical traits of this infection, though those parameters were common to other types of lung diseases and infections." (PMID 36428884, 2022). "IFNγ production was therefore not completely eliminated by MR1 blockade, but instead it was slowed down, which may be of paramount importance in an acute infection context such as S. aureus bacteraemia." (PMID 35056597, 2022). "Following infection, there is a shift towards lower pro-inflammatory reaction by higher levels of IL10 and TGFβ, and an increase in FoxP3 negative Treg co-expressing IL10, IFNγ, and TNF." (PMID 34684226, 2021). "Clearance of the infection requires CD4 T cells and appears to be independent of IFNγ." (PMID 34684248, 2021). "The protective activity of CD8+ T cells in defense against the infection with SFG and transitional rickettsiae as well as O. tsutsugamushi mainly relies on the cytotoxic activity of CD8+ T cells rather than the production of IFNγ." (PMID 34452021, 2021). "falciparum-specific IL-10 producing CD4+ T cells but not with IFNγ or TNFα producing CD4+ cells; however, these cells could not prevent infection prospectively." (PMID 34414129, 2021).
infection (continued). "However, this study also provided evidence for the importance of the Th2 response in acute schistosomiasis, with antigen-specific Th2 (IL-4, IL-5 and IL-13), but not Th1 (IFNγ), CD4+ T cells at week 4 post infection, significantly correlated to acute symptoms." (PMID 33953712, 2021). "To test whether ∆M36 infection would collaborate with TNF to induce the death of non-myeloid cells, we treated apoptosis-resistant endothelial cells with TNF, IFNβ, or IFNγ starting 1 hpi." (PMID 33126536, 2020). "When cells were treated with different concentrations of IFNγ for 24 h and then infected with EBOV∆VP30, we observed up to a 100-fold reduction in virus titers on day 2 post infection with no cytotoxicity, which is consistent with previous reports that IFNγ inhibits EBOV infection." (PMID 32528005, 2020). "Among the effectors that promote bacterial reduction, early secretion of interferon-gamma (INF-γ) by NK cells, DC, and Th1 cells greatly enhance macrophage-mediated killing of B. pertussis; mice lacking INF-γ developed a lethal infection after challenge with B. pertussis." (PMID 33178148, 2020). "However, in the early stage of the infection and in the absence of CD4 T cells, CD8 T cells and NK cells secrete IFNγ and are able to control the bacterial load." (PMID 33042146, 2020). "However, replication of the virus does continue to lead to some downregulation of inflammasome activation in IFNγ-treated macrophages because HSV-1/UV led to increased IL-18 production versus HSV-1, albeit not until 24 hours post infection." (PMID 32101570, 2020). "UV irradiating the virus prior to infection also leads to IL-18 production in unstimulated primary macrophages, but replication competent HSV-1 does not result in IL-18 release without pre-treatment with IFNγ." (PMID 32101570, 2020). "Effective control of this infection requires not just the action of antibodies specific for the parasite's variable surface glycoprotein (VSG) coat antigens, but also a pro-inflammatory immune response mediated mainly by IFNγ, TNF, and NO." (PMID 32655552, 2020). "At three months post-infection with low dose EBV, serum levels were biased towards proinflammatory cytokines and chemokines like TNFα, IL-8, and IL-6, while IFNγ and IL-10 were not significantly elevated, in contrast to what we observed after five weeks of high dose EBV infection." (PMID 31145756, 2019). "Second, the IFNγ ELISPOT may not be sensitive enough to detect all the responses, and some evidence suggests that the sensitivity of this method may vary during the infection." (PMID 30836625, 2019). "Our observation that IFNγ-dependent responses, such as the induction of IDO1, are not affected in bystander cells suggests a critical role for these cells in limiting the spread of infection." (PMID 29855501, 2018). "However, converse to what was seen in C57BL/6 mice, during early infection, female and castrated BALB/c expressed higher lungs levels of TNF, IFNG, IL12, iNOS, and IL17 than non-castrated males." (PMID 30619306, 2018). "Further support for the prominent role of STAT1 activation in the restriction of EHDV-TAU infection in LNCaP-JAK1 cells and in EHDV-TAU induced oncolysis by non-productive infection comes from the observed effects of IFNγ, known to mediate antiviral effects through STAT1 homodimer formation." (PMID 29441069, 2018). "Mtb-infection alone did not significantly affect MHC class II expression, and consistent with previous studies, Mtb significantly impaired the induction of MHC class II by IFNγ pretreatment." (PMID 29782535, 2018). "At later timepoints after infection, the anti-leishmania T cell response in CCL7 KO C57BL/6 mice resembled that of their WT C57BL/6 counterparts with a predominance of IFNγ producers suggesting CCL7 is not required for the priming of a protective anti-leishmania Th1 response." (PMID 30671055, 2018).